CRP (C-reactive protein)
Diseases named in the same sentence as CRP in open-access papers (continued):
Sharing a sentence is not in itself a finding about the gene and the disease.
COVID-19 (continued). "A total of 70.67% of COVID-19 patients had increased CRP, sharing a median of 13.63 mg/L, which was higher than that of the flu group (P = 0.0372)." (PMID 33834012, 2021). "Nearly 2/3 of the COVID-19 patients had elevated CRP and 40% had elevated lactate dehydrogenase levels." (PMID 33988463, 2021). "The KL-6, CRP, Leukocyte count and Neutrophil count are significantly higher in patients with severe COVID-19 compared with patients with moderate COVID-19, while the lymphocyte count is lower." (PMID 33907520, 2021). "CRP has been used as a predictor in several previous studies of COVID-19 prediction models, and disease progression in MERS, influenza-infected and community-acquired pneumonia patients." (PMID 34195215, 2021). "Ground-glass opacity and patchy shadows with bilateral lesions in computed tomography analysis results, reduction in the lymphocytes accounts, and increase in C-reactive protein (CRP) accounts constitute the typical biological characteristic of COVID-19." (PMID 34136533, 2021). "MHD patients with COVID-19 had elevated infection-related biomarkers, including CRP, ESR, procalcitonin, IL-6, IL-2R and TNF-α, which likely reflected an exacerbated inflammatory response." (PMID 33967613, 2021). "CRP does not normally elevate significantly in mild viral respiratory infection however, significant increase of CRP has been reported in COVID-19 patients." (PMID 33727641, 2021). "In COVID-19, besides high cytokine levels, lymphocyte count is usually reduced with elevations in levels of D-dimer, C-reactive protein (CRP), ferritin, and procalcitonin that also support the development or continuation of cytokine storm in COVID-19 patients." (PMID 34829920, 2021). "Our study also demonstrated that CRP and IL-6 levels were higher in the critical COVID-19 group and correlated positively with NHR." (PMID 34589058, 2021). "All these abnormalities evidenced on TTE were significantly correlated with the severity of the initial pulmonary injury and/or the level of CRP, as well as with the number of weeks since the acute phase of COVID-19 and the number of remaining symptoms." (PMID 34204032, 2021). "During our study, increased CRP levels in COVID-19 patients emerged with reduced PAB concentrations." (PMID 34242179, 2021). "Higher CRP values have been positively correlated with increased mortality in COVID-19 patients in similar study cohorts." (PMID 34868744, 2021). "In our observational study on 60 high viremic patients with acute COVID-19, we found that seven patients (11.66%) not only had viral shedding in urine but also presented higher inflammation markers, such as CRP, IL-6 as well as Fibrinogen." (PMID 34575171, 2021). "We have shown that the damage parameters (i.e., DAMPs) such as LDH have a strong correlation with CRP in COVID-19 patients." (PMID 34539644, 2021). "High C-reactive protein (CRP), sedimentation rate, lactate dehydrogenase, and serum ferritin (SF) have been frequently reported in COVID-19 patients." (PMID 34356272, 2021). "In brief, 11 women and 26 men COVID-19 patients, with a median age of ∼62 years and evidence of systemic inflammation (indicated by C-reactive protein) of which 17 displayed GI symptoms (diarrhea and/or nausea and/or vomiting) were included in this study." (PMID 33438988, 2021). "Although this was an uncontrolled study, it further supports the link between acute inflammatory biomarkers such as IL-6 and CRP with COVID-19 pathogenesis." (PMID 34452063, 2021). "Consistent with baseline results, the number of lymphocytes (p=0.0017) and levels of CRP (p=0.0009) at the time of PD-L1 measurement significantly correlated with the number of deaths from COVID-19." (PMID 34163490, 2021). "CRP is the biomarker that most strongly correlates with COVID-19 progression, is significantly elevated during the early stage of inflammation and also prior to indications of critical findings with CT." (PMID 34447386, 2021).
COVID-19 (continued). "The impact of these findings support the routine assessment of serum CRP as an adjunct in the early diagnosis and assessment of illness severity of hospitalized patients with COVID-19." (PMID 33683344, 2021). "Another result from the present study is the negative association of SARS-CoV-2 IgG antibodies with pulmonary inflammatory markers (SAA, CRP, ferritin) in our cohort of COVID-19 patients." (PMID 33760825, 2021). "In the COVID-19-positive group, the cortisol and CRP levels were positively correlated (rho: 0.482; P < 0.001)." (PMID 34190873, 2021). "Our logistic regression analysis showed that older age, higher BMI, elevated CRP, and elevated ferritin were the significant predictors of newly diagnosed DM among COVID-19 patients (p < 0.001)." (PMID 34449740, 2021). "Multivariate regression showed that age>65, male sex, AaDO2%, N/L, and CRP values were the main statistically significant variables able to identify COVID-19 patients needing an in-hospital observation period." (PMID 34790472, 2021). "It has been observed that CRP is a biochemical parameter that is usually increased in patients with COVID-19." (PMID 34462686, 2021). "The aim of the present longitudinal cohort study was to determine whether elevated CRP levels measured in the early stages of COVID-19 were associated, independently from the albumin levels, with higher 14-day mortality in geriatric patients hospitalized for COVID-19." (PMID 34506514, 2021). "These factors explain the strong temporal correlations in severe COVID-19 patients observed between increases in the levels of IL-6, CRP, and D-dimer, and with lymphopenia and the development of progressive organ failure." (PMID 33550983, 2021). "The value of PCT and CRP to detect secondary infections in critically ill COVID-19 patients treated with DEXA was investigated for both D+T− and D+T+ groups as well as for the total second cohort (D+T−/+)." (PMID 34353339, 2021). "This coagulopathy appears to be a core pathophysiology of COVID-19 as rising D-dimer levels, correlate with a poor prognosis, as do rising levels of IL-6 and CRP." (PMID 33833683, 2021). "In contrast, P11 and P12, who suffered from severe courses of COVID-19, had CRP levels below 100 mg/l on admission, but after one week the CRP level of P12 increased to over 100 mg/l, while the CRP level of P11 decreased." (PMID 33903660, 2021). "This comprehensive meta-analysis found age, cerebrovascular disease, CRP, LDH and cTnI to be the most important risk-factors that predict severe COVID-19 outcomes and will inform clinical scores to support early decision-making." (PMID 34324560, 2021). "Correlation analyses are mainly associated with increased levels of IL-6 and CRP and decreased CD4+ cell counts with the severity of COVID-19 in people with diabetes." (PMID 34786431, 2021). "He spent 20 days in the ICU with elevated inflammatory biomarkers (C-reactive protein and D-dimer) and increased peaks of neutrophil-to-lymphocyte ratio, which is uncommon for teenagers diagnosed with COVID-19." (PMID 33777976, 2021). "The severity of COVID-19 is attributed to the inflammatory status, presented as an increased inflammatory biomarker such as C-Reactive Protein (CRP), Interleukin 2 (IL-2), and Interleukin 6 (IL-6), which are predictors of mortality." (PMID 34903765, 2021). "Age, neutrophil-to-lymphocyte ratio (NLR), D-dimer, and C-reactive protein reported during admission were identified as mortality predictors for COVID-19 patients using least absolute shrinkage and selection operator (LASSO) regression." (PMID 34786318, 2021). "These metabolic alterations correlated not only with disease severity, but also with the GAP symptoms and two prognostic predictors of COVID-19 mortality: lymphopenia and CRP levels." (PMID 33946479, 2021).
COVID-19 (continued). "During the COVID-19 outbreak, the findings of several studies have demonstrated a positive correlation between CRP and lung lesions in COVID-19 patients, with significant CRP alterations being observed in non-survival patients." (PMID 34778296, 2021). "Another study showed that CRP levels were strongly correlated with disease severity and lung lesion in patients with COVID-19." (PMID 34462686, 2021). "Based on our results, CRP, d-dimer, and ferritin levels at admission to hospitals represent simple assessment factors for COVID-19 severity and the treatment decisions at the hospital setup." (PMID 34314447, 2021). "The elevation of acute phase markers is also reported in the literature as a potential COVID-19 marker, namely PCR (C-reactive protein), vs. (erythrocyte sedimentation rate), lactate dehydrogenase (LDH), and ferritin." (PMID 33807607, 2021). "Hematological abnormalities, including leukopenia, lymphopenia, and thrombocytopenia, are common among COVID-19 patients, as well as elevated levels of C-reactive protein (CRP), alanine aminotransferase (ALT), lactate dehydrogenase (LDH), and ferritin." (PMID 34981695, 2021). "As it was previously demonstrated, Avifavir® itself enabled SARS-CoV-2 viral clearance in 62.5% of patients within 4 days of therapy but had little effect on the concentration of CRP, which is a marker of the severity of COVID-19." (PMID 34199134, 2021). "There was a significant difference between the COVID-19 patients and the healthy control group with regard to the presence of comorbidities, total leucocytic count, lymphocytic count, CRP, serum LDH, ferritin and D-dimer (p < 0.01)." (PMID 34071309, 2021). "Fatal COVID-19 is associated with acute respiratory distress syndrome (ARDS) and elevated markers of systemic inflammation including IL-6 and C-reactive protein (CRP), often accompanied by peripheral blood neutrophilia and lymphopenia." (PMID 33692097, 2021). "Alternatively, our experience suggests that patients with severe COVID-19 showing a high basal ratio of ferritin/CRP needs combinational treatment of corticosteroids and tocilizumab." (PMID 34631752, 2021). "COVID-19 patients admitted to ICU had significantly elevated GGT activity and inflammatory markers levels (WBC count, CRP, IL-6, ferritin) than the rest of COVID-19 patients." (PMID 34680053, 2021). "We first assessed the natural course and effects of cessation of dexamethasone (DEXA) treatment on PCT and CRP levels in critically ill COVID-19 patients." (PMID 34353339, 2021). "Clinically, the main symptoms of severe COVID-19 patients include fever, leukopenia, lymphopenia, thrombocytopenia, C-reactive protein increase, and cytokines abnormity." (PMID 34088324, 2021). "The COVID-19 (+) patient median values for pro-inflammatory markers (C-reactive protein, ferritin, fibrinogen, and IL-6) were all increased by 1.5–2.0-fold greater than that observed in COVID-19 (−) patients." (PMID 35087853, 2021). "CRP is an inflammatory marker easily and commonly measured, which appears to be increased in COVID-19 patients." (PMID 33430129, 2021). "Serum Ca levels were found to correlate inversely with inflammation as assessed by white blood cell count, IL-6, and CRP levels, as well as D-dimer and procalcitonin levels, as well as organ injury in COVID-19." (PMID 33920813, 2021). "In a retrospective cohort study, the predictive power of several reported previously identified prognosis marker [circulating lymphocytes, IL-6, lactic acid, procalcitonin, CRP (C-reactive protein), and viral load] of 142 COVID-19 patients were assessed." (PMID 35174189, 2021). "Similar to our finding, previous studies have shown that lymphopenia and elevated CRP are indicators of poor outcome for COVID-19 patients." (PMID 33243228, 2020).
COVID-19 (continued). "If the patients who were admitted to the hospital had higher fever and symptoms of anorexia, biochemical examination showed higher CRP and lymphopenia; the patients is then more likely to progress to severe COVID-19." (PMID 32571410, 2020). "In this study, we retrospectively analyzed the clinical and biological characteristics of the COVID-19 infected patients, and investigated the ability of CRP to predict at an earlier time the disease severity, in comparison with other biomarkers." (PMID 33312067, 2020). "When compared to younger populations, Liu K and colleagues demonstrated that older COVID-19 patients (≥60 years old) had significantly lower lymphocyte proportion as well as significantly higher CRP levels." (PMID 32765959, 2020). "Because COVID-19 was managed as Class A infectious disease, this study only performed routine blood tests, C-reactive protein, chest HRCT, throat swab SARS-CoV-2 nucleic acid testing, but not blood biochemical tests in the patients." (PMID 32948121, 2020). "Linear regression analysis showed that the PNI in patients with COVID-19 was negatively correlated with the CRP level and positively correlated with the hemoglobin level (r = −0.454, P < 0.001; r = 0.332, P < 0.001, respectively)." (PMID 33521032, 2020). "COVID-19 patient-level data show an OR of 3.4 with 95% CI (2.15 to 5.4) for high CRP in severe COVID-19 patients." (PMID 32876941, 2020). "Overall inflammatory burden, measured by quantitative CT data (i.e., VoD at baseline CT) and C-reactive protein levels, were the most important variables for outcome prediction in COVID-19 patients." (PMID 32592118, 2020). "Consistent with recent literature reports, our cohort also observed that the most common laboratory abnormalities in COVID-19 patients were lymphopenia, elevated C-reactive protein, and elevated D-dimer." (PMID 33062082, 2020). "In conclusion, we found worsening clinical status in COVID-19 to be associated with fever, cough, dyspnea, pneumonia, any CT findings, any GGO, lymphocytopenia, elevated WBC, elevated CRP, elevated ALT, elevated AST, increased age and male sex." (PMID 32941548, 2020). "Compared with the baseline before infection, HD patients with COVID-19 had lower lymphocytes, albumin and glucose, and higher D-dimer, albumin, phosphorus, lactate dehydrogenase, and CRP." (PMID 32722980, 2020). "The hazard ratio of prognosis for risk of COVID-19 identified CEA, WBC, CRP, PCT, Fer, D-dimer, Neu%, and L% as independent prognostic factors." (PMID 33537326, 2020). "Studies showed that increased inflammatory markers in serum of COVID-19 patients, especially CRP, procalcitonin, IL-6, and erythrocyte sedimentation rate (ESR), were positively correlated with the severity of COVID-19." (PMID 33391935, 2020). "In the two cases of severe COVID-19, the levels of CRP, PCT, serum ferritin, IL-6, and IL-10 were significantly increased, whereas the numbers of CD3+, CD4+, CD8+ T lymphocytes, and CD16 + CD56 natural killer cells were decreased." (PMID 32574284, 2020). "When considering variables on admission, dyspnoea, lymphopaenia, and increased AST and CRP levels were independent prognostic factors for severe course of COVID-19." (PMID 32472191, 2020). "Of the blood tests proposed as possible markers of outcome in COVID-19, the lymphocyte count was chosen by 64.4%, D-dimer by 64.4%, C-reactive protein (CRP) by 59.3%, and the SARS-CoV-2 viral load by 42.3% of the study subjects." (PMID 32748880, 2020). "In this article, we identify inflammatory markers (interleukin-6, D-dimer, neutrophil-to-lymphocyte ratio and hs-CRP) as predictors of COVID-19 mortality." (PMID 33392056, 2020). "To date, clinical and laboratory features such as lymphopoenia, elevated C-reactive protein (CRP), D-dimer and liver enzymes have been associated with severe COVID-19." (PMID 33148349, 2020).
COVID-19 (continued). "The absolute numbers of total WBCs (A), NEU (B), LYM (C), MON (D), CRP (E), and D-D (F) in the peripheral blood of mild (blue line) and severe (red line) COVID-19 patients were analyzed at different time points after hospital admission." (PMID 32484453, 2020). "In severe COVID-19 cases, cytokine storm notably increases the production of CRP, and as such a stronger correlation between cytokine storm and high CRP is achieved." (PMID 32876941, 2020). "Compared to controls, pregnant COVID-19 patients showed significantly lower numbers of blood lymphocytes and higher numbers of neutrophils, as well as higher levels of C-reactive protein and total bilirubin." (PMID 33117727, 2020). "This study identified that an estimated glomerular filtration rate < 90 ml/min/1.73, elevated cardiac troponin I, C-reactive protein ≥ 25 mg/L and procalcitonin ≥ 0.05 ng/ml were predictors of mortality in COVID-19 patients." (PMID 33365277, 2020). "Age, neutrophil-to-lymphocyte ratio, d-dimer and C-reactive protein obtained on admission were identified as predictors of mortality for COVID-19 patients by LASSO." (PMID 32867787, 2020). "These further identified the inflammatory cytokines neutrophils and CRP as predictors of the adverse clinical outcome of COVID-19." (PMID 33192519, 2020). "In consistency with previous report, the median value of CRP in controls is 0.4 mg/L while in COVID-19 patients is 5.56 mg/L, indicating inflammation." (PMID 32475230, 2020). "Among the clinical features of COVID-19 patients, there is a very high number of circulating inflammatory molecules, including C reactive protein (CRP) and pro-inflammatory cytokines." (PMID 32471272, 2020). "Plasma TnT levels in patients with COVID-19 correlated significantly with both plasma high-sensitivity C-reactive protein levels (β = 0.530, P < .001) and plasma NT-proBNP levels (β = 0.613, P < .001)." (PMID 32219356, 2020). "The multivariate analysis revealed that CRP (p = 0.004), PaO2/FiO2 (p = 0.002), and cTnI (p = 0.016) were independent prognostic factors for predicting the mortality of COVID-19 patients." (PMID 32850612, 2020). "Common laboratory findings in COVID-19 are a decreased lymphocyte count and an increased C-reactive protein (CRP) level." (PMID 33542917, 2020). "We found that there were differences in some clinical and radiological data after symptom onset between patients with moderate and severe COVID-19, including body temperature, CRP level, and range of pulmonary involvement." (PMID 33204376, 2020). "Lastly, COVID-19 patients admitted to ICU had a significantly higher CRP level (p < 0.001), plasma creatinine (p = 0.002), and Hs-cTnI (p < 0.001)." (PMID 33282891, 2020). "Laboratory findings showed high lactic acid level (2.1 mmol/L) and C-reactive protein (CRP, 48.8 mg/L), and low white blood cell count (1.96 × 109/L) in a 65-year-old Chinese man, who was diagnosed with severe COVID-19." (PMID 32560646, 2020). "Patients with severe COVID-19 had higher body temperature and CRP level, and a wider range of pulmonary involvement after symptom onset." (PMID 33204376, 2020). "Neutrophil and lymphocyte counts, aspartate aminotransferase, C-reactive protein, and ferritin were higher in the COVID-19 moderate severity patient group." (PMID 33239068, 2020). "We also discovered there were higher levels and proportion of the elevation of LDH, IL-2R, IL-6, IL-8, IL-10 and TNF-α, furthermore, there were only higher levels of CRP and ferritin in the critically ill COVID-19 patients." (PMID 32788884, 2020). "Consistent with adult data, LDH and CRP appear to be positively correlated with COVID-19 severity in our study." (PMID 32865382, 2020). "Reflecting the general population, presenting with fever, dyspnea, gastro-intestinal symptoms, higher levels of CRP, or ferritin were also indicators of COVID-19 severity in the cancer population." (PMID 32903324, 2020).